IL6 (interleukin 6)
Diseases named in the same sentence as IL6 in open-access papers (continued):
Sharing a sentence is not in itself a finding about the gene and the disease.
steatosis (continued). "The administration of exogenous IL-6 (BD+IL-6+LT) increased IL-6 levels in both types of livers but livers obtained from DBDs were only protected against damage and inflammation in the absence of steatosis." (PMID 37593740, 2023). "Indeed, lack of IL-6, or reduced IL-6 levels by neutralising antibody, have been shown to increase lipid accumulation and exacerbate HF diet-induced steatosis in rodents." (PMID 35470093, 2022). "Interestingly and importantly, xenobiotic-induced inflammatory response was significantly higher in the NASH MT, as compared to the steatosis MT (i.e., ten-fold increase in IL6 in NASH MT, as compared to the steatosis MT) which were again substantially higher than the healthy MT." (PMID 34668024, 2022). "Furthermore, a steatosis liver, especially in the non-alcoholic steatohepatitis (NASH) stage, releases several proinflammatory cytokines, such as interleukin-1, interleukin-6 and tumor necrosis factors, involved in the activation of deleterious inflammatory pathways." (PMID 33511140, 2020). "We also found that IL6 and TNFα, two important proinflammatory adipocytokines hugely expressed in the adipose tissue of obese human subjects and patients with IR, were overexpressed in the liver of NAFLD MO women with NASH compared to those with simple steatosis." (PMID 25474087, 2014). "However, other studies have shown that IL-6 deficiency or blockade reduced liver inflammation without affecting the development of steatosis suggesting a role for IL-6 only in promoting liver inflammation." (PMID 24039859, 2013). "Despite the marked steatosis, iVP16LXRα mice did not present an increased hepatic inflammatory signature, as indicated by the halved expression of Tumour Necrosis Factor α (Tnfα), Tumour Growth Factor β (Tgfβ) and Interleukin 6 (Il6) as well as the decreased level of the macrophage marker F4/80." (PMID 38824560, 2024). "Whereas other steatosis-promoting inflammatory cytokines, such as TNF-α and IFN-γ, are also increased in mice lacking IL-10, their effect is masked by IL-6/STAT3 anti-lipogenic properties." (PMID 41514930, 2025). "Inhibiting explicit IL-6 activity alone did not predict any ALT elevations, while tocilizumab-mediated steatosis and ROS elevations alone predicted ALT elevations for all individuals." (PMID 37298645, 2023). "HMGB1 kinetics did not correlate with either IL-6 or TNF-α, but with the degree of graft steatosis and postoperative ALT levels." (PMID 36338535, 2022). "The lack of inflammatory cytokines as steatosis progressed correlated with decreasing activation of NF-κB p65, a transcriptional activator of TNF-α and IL-6." (PMID 31034519, 2019). "Unlike current PCLSs models, which show only steatosis, lipid deposition, and lipotoxicity, human PCLSs under GFIPO after 96 h exhibited markers of liver inflammation, including up-regulated inflammatory genes (TNFα, IL6, and IL1β) and cytokines (TNFα, IL6, IL8), detectable up to 96 h." (PMID 38474754, 2024).
cardiac hypertrophy (186 papers, 2007 to 2026). "Apart from this function, IL-6 causes cardiac muscle dysfunction through the sirtuin 1 pathway and promotes cardiac hypertrophy through the activation of fgp130." (PMID 39456869, 2024). "Cardiac fibroblasts induced IL-6 signaling in myocytes to cause cardiac hypertrophy via the p38α pathway." (PMID 38256155, 2024). "High levels of IL-6 have also been linked to the severity of Chagas disease in both humans and experimental models, with the development of cardiac hypertrophy, arrhythmias and cardiac fibrosis." (PMID 39598539, 2024). "Previous studies have shown that proinflammatory cytokines, such as TNF-α, IL-1β, and IL-6, are closely associated with myocardial fibrosis, pathological cardiac remodeling, and myocardial hypertrophy." (PMID 38158445, 2023). "Inhibition of Rho leads to a decreased IL-6 secretion, which also contributes to the beneficial effects of statins on cardiac hypertrophy, as IL-6 is associated with reduced left ventricular mass in hypertensive patients." (PMID 37887864, 2023). "Thoracic aorta constriction (TAC)-induced hypertrophy and fibrosis in the LV are ameliorated by IL-6 ablation in mice, indicating that IL-6 plays a crucial role in cardiac hypertrophy caused by TAC." (PMID 37047522, 2023). "Previous studies reported that inflammatory factor, such as TNF-α and IL-6, cause cardiac hypertrophy and fibrosis through regulate the cardiac inflammatory response." (PMID 36471367, 2022). "An experiment has proved that the gene deletion of IL-6 is linked to the decrease of cardiac hypertrophy and fibrosis after angiotensin II stimulation in mice model." (PMID 34504432, 2021). "In the treated patients, the associations between synovial hypertrophy and any cytokines were diminished, although synovial vascularity and echogenicity correlated with IL-6 and VEGF (p < 0.05)." (PMID 30630515, 2019). "Cardiac fibroblast-specific p38α MAPK causes cardiac ventricular remodeling and fibrosis promotes cardiac hypertrophy via regulating interleukin-6 signaling." (PMID 31849653, 2019). "IL-6 has been implicated as a cause of cardiac hypertrophy, and an increase in IL-6 levels is a risk factor for sudden cardiac death in patients with CAD." (PMID 30858306, 2019). "Its effects on cardiac contractility reduction and LV (left ventricular) remodeling- fibrosis, hypertrophy and dilatation, support the association between IL-6 and development of end-organ damage in hypertensive patients." (PMID 31186952, 2019). "Overexpression of IL-6 in the myocardium in acute MI (AMI) appears to be associated with the mechanism of cardiac hypertrophy." (PMID 21792366, 2011). "IL-6 has been associated with inflammation and cardiac hypertrophy in HCM and increased IL-6 levels may contribute to disease progression." (PMID 40843168, 2025). "However, chronic elevation of IL-6 within the heart has been associated with cardiac disease progression and is known to promote cardiac fibrosis, hypertrophy and ventricular dysfunction." (PMID 35406763, 2022). "Furthermore, IL-6 is associated with cardiomyopathies such as cardiac hypertrophy and fibrosis in experimental animals and in the general human population." (PMID 32973791, 2020). "Besides, elevated cardiac IL-6 is also associated with cardiac hypertrophy and fibrosis in the general population and in rodents." (PMID 33584641, 2020). "Together these data indicate that cardiac DAMPs can stimulate IL-6 transcription and protein secretion in a p38α-dependent manner; a mechanism that may underlie our in vivo observations on cardiac hypertrophy." (PMID 29601781, 2018). "STAT3 mediated by IL-6 is another major cause to cardiac hypertrophy." (PMID 25122164, 2014). "Likewise, normal cardiac myocytes might also be influenced by IL-6 secreted from the neoplastic cardiac myxoma cells and might cause ventricular hypertrophy in a patient with cardiac myxoma." (PMID 38396907, 2024).
cardiac hypertrophy (continued). "In addition, IL-6 infusion in healthy animals directly induces cardiomyocyte hypertrophy and cardiac fibrosis 57; in contrast, the deletion of IL-6 decreased pressure overload-induced ventricular hypertrophy 58, suggesting a direct pathogenic effect of IL-6 on the heart." (PMID 35173530, 2022). "Particularly, it provides evidence that CKD-associated cardiac hypertrophy correlates with reduced eGFR and soluble Klotho and Vitamin D levels, and is indicative of a generalized pro-inflammatory status, as evidenced by increased levels of IL-6, ACR, PTH, P and FGF23." (PMID 30934737, 2019). "Additional research using animal models that show the profibrotic function of IL-6 by inducing ventricular hypertrophy and fibrosis by its infusion supports this theory." (PMID 40428204, 2025). "IL-6, secreted from cardiac fibroblasts, contributes to cardiac hypertrophy through the p38 MAPK pathway, which regulates pro-inflammatory cytokine biosynthesis at the transcriptional and translational levels." (PMID 40711721, 2025). "This study delves into the role of YAP in ISO-induced cardiac hypertrophy and how it exerts this effect through the regulation of the IL-6/STAT3 signaling pathway in CFs." (PMID 40919415, 2025). "Mice suffering from pressure overload–induced cardiac hypertrophy exhibited elevated levels of both IL-6 and IL-1 β." (PMID 40711721, 2025). "In rodent models, IL-6 contributes to increased collagen deposition within the cardiac muscle, contributing to ventricular hypertrophy and stiffness." (PMID 41284707, 2025). "Our findings demonstrated that verteporfin protects the heart from ISO-induced myocardial hypertrophy through mechanisms involving the regulation of the IL-6/STAT3 pathway in cardiac fibroblasts (CFs)." (PMID 40919415, 2025). "A cardiac-specific miR-30a-5p sponge also promoted D-gal-induced cardiac hypertrophy and myocardial IL-1β and IL-6 levels, along with an increase in β-gal-positive cells." (PMID 39511427, 2024). "IL‐6 promoted cardiac hypertrophy, proliferation of cardiac fibroblasts, and collagen production in diabetic rats." (PMID 38617433, 2024). "CT-1, a member of the IL-6 cytokine family, is known for its role in cardiac hypertrophy and inflammation." (PMID 39772209, 2024). "Pathological cardiac hypertrophy was also reported to be a classic feature of sickle cell disease, where hemolysis increased IL-6 expression in mice." (PMID 38256155, 2024). "KO also promoted D-gal-induced cardiac hypertrophy and increased myocardial IL-1β and IL-6 levels, as well as the number of β-gal-positive cells." (PMID 39511427, 2024). "Mice undergoing excessive exercise training were observed to show signs of pathologic cardiac hypertrophy and increased expression of pro-inflammatory cytokines, including IL-6." (PMID 38256155, 2024). "For example, phagosome formation, IL-6 signaling, and cardiac hypertrophy (enhanced) pathways were among the top pathways in both stable CAD and remote MI." (PMID 38776872, 2024). "Our results showed that the expression of RIPK1 and the phosphorylation of MLKL were significantly up-regulated in the myocardium of WT mice with myocardial hypertrophy, and the levels of serum IL-6 and TNF-α were increased." (PMID 37833985, 2023). "The conditioned medium derived from hCad-11-Fc stimulated fibroblasts activated cardiomyocytes and pre-treatment with IL-6 antibody blocked this conditioned medium-induced heart hypertrophy." (PMID 37047522, 2023). "Multiple studies evidenced that elevated IL-6 concentrations in the myocardium can increase muscle mass, known as cardiac hypertrophy." (PMID 37637634, 2023). "IL-6 promotes an inflammatory response, contributing to cardiac hypertrophy when remains chronically elevated." (PMID 37676301, 2023). "We also found that IL-6 is important for the activation of the MAPK pathway in cardiomyocytes and that blocking IL-6 inhibited cardiac hypertrophy." (PMID 37047522, 2023).
cardiac hypertrophy (continued). "Another study showed that increasing circulating heme significantly elevated plasma IL-6 and the expression of cardiac hypertrophy markers in Townes sickle cell mice." (PMID 36830749, 2023). "We provided evidence obtained from both in vitro cell culture system and in vivo TAC mouse model that Cad-11 plays a role via IL-6 in both myocardial hypertrophy and fibrosis of the left ventricle induced by pressure overload." (PMID 37047522, 2023). "Together, these results indicate that Cad-11 activates cardiac hypertrophy through paracrine IL-6 signaling between fibroblasts and cardiomyocytes." (PMID 37047522, 2023). "Another study shows that activation of mitogen-activated protein kinase and Ca2+/calmodulin-dependent protein kinase II- signal transducers and activators of transcription signaling pathways 3 by IL-6 also induce cardiac hypertrophy after a cardiac insult." (PMID 38137440, 2023). "The pivotal role of IL-6 and Angiotensin II (AngII)-induced collagen deposition during cardiac hypertrophy has also been well-documented." (PMID 37637634, 2023). "Cardiac hypertrophy can occur in response to proinflammatory cytokines, such as IL-6 and IL-1β, and can be required for maintenance of cardiac homeostasis." (PMID 34669512, 2022). "Consistently, K2KO hearts showed increased transcription of cardiac hypertrophy genes (e.g., Nppa) and inflammation genes (e.g., Il6)." (PMID 34793333, 2022). "For example, leptin treatment of cardiomyocytes from humans and neonatal rats has been found to induce TNF-α-/IL-6-mediated redox stress and cardiac hypertrophy." (PMID 36684585, 2022). "According to our previous studies, BSJY can promote the expression of the ERK pathway and inhibit the expression of the TNF-α, MCP-1, and IL-6, which would suppress ventricular hypertrophy and inflammatory responses." (PMID 35033168, 2022). "IL-6 not only binds to IL-6R on the surface of cardiomyocytes and induces myocardial hypertrophy via the MAPK and CaMKII-STAT3 pathways but also binds to IL-6R on the surface of cardiac fibroblasts and activates them." (PMID 36299447, 2022). "The results of the present study revealed that expression of RIPK1 and phosphorylation of MLKL were significantly upregulated in the myocardium of WT myocardial hypertrophy mice, and the levels of serum IL-6 and TNF-α were increased." (PMID 36046685, 2022). "In the development of cardiac hypertrophy, the increased expression of IL-6, TNF-α, and IL-1β is closely related to Collagen I and Collagen III deposition." (PMID 36270989, 2022). "Mechanistically, we revealed that miR-320 mimics aggravated the pressure overload and induced cardiac hypertrophy and fibrosis via the IL6/STAT3/PTEN axis." (PMID 34582362, 2021). "Our previous work demonstrated that RORα mitigated Ang II-induced cardiac hypertrophy through the regulation of cardiomyocyte IL6 and STAT3 signaling." (PMID 34756888, 2021). "IL-6 plays a central role in HIMF-induced cardiac hypertrophy and fibrosis that is mediated by activating the MAPK and CaMKII-STAT3 pathways." (PMID 34336840, 2021). "Over the past two decades, many studied have indicated that IL-1β, IL-6, and TNF-α are closely implicated in cardiac fibrosis, pathological cardiac remodeling, and cardiac hypertrophy." (PMID 34194329, 2021). "Many pro-inflammatory factors are involved in pressure overload-induced cardiac hypertrophy in mice, including IL-1β, IL-6, IL-18, and TNF-α." (PMID 34168567, 2021). "In an ischemia/reperfusion-induced myocardial injury model, systemic or intracoronary injection of FSTL1 reduced the expression of inflammatory cytokines such as TNF-α and IL-6, thereby improving cardiac hypertrophy and dysfunction." (PMID 33936382, 2021). "For example, some inflammatory cytokines such as TNF-α, IL-1β, and IL-6 directly induce cardiac hypertrophy and correlated with the severity of hypertrophy." (PMID 33324685, 2020).
cardiac hypertrophy (continued). "The results showed that LCZ696 significantly improved heart dysfunction, cardiac hypertrophy, and fibrosis and inhibited the expression of proinflammatory factors IL-6, IL-1β, and TNF-α in the circulating blood and heart tissues of mice." (PMID 32420365, 2020). "The specific mechanisms by which hemolysis-induced IL-6 contributes to the development of cardiac hypertrophy in SCD warrants future investigation." (PMID 32973791, 2020). "These conclusions indicate that IL-6 plays a complex role in various stimulation-induced cardiac hypertrophy, and the function of IL-6 in cardiac hypertrophy remains to be investigated." (PMID 33324685, 2020). "Many previous reports have demonstrated that IL‐6/IL‐6R signaling induces cardiac remodeling including myocardial hypertrophy." (PMID 32302067, 2020). "The divergence ascribed to the results of present studies makes the role of IL‐6 in the development of pressure overload‐induced cardiac hypertrophy and HF in mice complicated." (PMID 32164044, 2020). "The results showed that IL-6 KO significantly reversed cardiac hypertrophy, alleviated cardiac dysfunction, decreased pro-senescence marker mRNA expression and increased anti-senescence marker expression." (PMID 33099539, 2020). "In Ang II-infused mice, IL-6 significantly increases cardiac fibrosis and aggravates cardiac hypertrophy." (PMID 33099539, 2020). "PlGF promotes cardiac hypertrophy via endothelial cell release of NO which induces cardiomyocyte growth and by inducing the secretion of paracrine factors (IL-6, IL-1b, Cxcl1) from endothelia and fibroblasts that promote cardiac adaptation and hypertrophy." (PMID 33584641, 2020). "In this study, we assess direct heme induction in vivo of IL-6 and genes relevant to cardiac hypertrophy in the heart of sickle cell mice." (PMID 32973791, 2020). "We find that experimental administration of heme 50 μmoles/kg body weight induces IL-6 expression directly in vivo and induces gene expression markers of cardiac hypertrophy in SS mice." (PMID 32973791, 2020). "Among various kinds of pro‐inflammatory cytokines, interleukin (IL)‐6 has been reported to be involved in cardiac hypertrophy and fibrosis." (PMID 32302067, 2020). "During myocyte hypertrophy, genetic deletion of IL-6 has been shown to ameliorate cardiac dysfunction and suppress Ang II-induced cardiac hypertrophy, suggesting that it has an exacerbating role in hypertrophic remodeling." (PMID 33324685, 2020). "In the present study, we have observed enhanced expression of inflammatory genes such as TNF-α, IL-6, and IL-1β in hypertrophy heart." (PMID 32082481, 2020). "Chronic long-term signaling of IL-6 induces inflammation and promotes cardiac hypertrophy in other models." (PMID 32973791, 2020). "In a similar model, we established a role for cardiac fibroblast p38α in stimulating cardiac hypertrophy after chronic β-adrenergic stimulation and uncovered a potential role for IL-6 acting as a paracrine inducer of cardiomyocyte hypertrophy in this context." (PMID 31586031, 2019). "Recent fibroblast-targeted transgenic mouse studies provide support for fibroblast-derived IL-6-driving cardiac hypertrophy in vivo, with p38α playing a key role." (PMID 31394846, 2019). "IL-6 is a pleiotropic pro-inflammatory cytokine that promotes cardiac fibroblast proliferation and fibrosis as well as cardiac hypertrophy through its actions on cardiomyocytes and is readily secreted by cardiac fibroblasts in culture." (PMID 31586031, 2019). "In our animal model of cardiac hypertrophy, the activity and the expression level of several signal proteins were increased, including IL-6, JAK and p-STAT3." (PMID 29433438, 2018). "In summary, our study reveals an important role for p38α, specifically in cardiac fibroblasts, in stimulating cardiac hypertrophy after chronic β-adrenergic stimulation, potentially via an IL-6–dependent mechanism." (PMID 29601781, 2018).